PTN (pleiotrophin)
Diseases named in the same sentence as PTN in open-access papers (continued):
Sharing a sentence is not in itself a finding about the gene and the disease.
melanoma (10 papers, 2002 to 2024). A malignant, usually aggressive tumor composed of atypical, neoplastic melanocytes. "Moreover, midkine (MDK), a protein related to PTN, was recently reported to be associated with aggressive immune evasive melanoma, suggesting that these small heparin-binding neurotrophic factors might have unexplored important functions in malignancy." (PMID 36828390, 2023). "PTN is overexpressed in melanoma, and PTN exerts multiple pro-tumorigenic functions through its activation of RPTPβ/ζ." (PMID 39336822, 2024). "Accordingly, knocking down PTN in melanoma cell lines recapitulates the effect of menin overexpression on tumorigenesis." (PMID 39336822, 2024). "So far, two studies exploring anti-PTN antisense RNA and ribozyme targeting to establish PTN as an attractive target for the therapy of melanoma." (PMID 28562667, 2017). "As mentioned in the introduction, PTN promotes the invasion and metastasis in many different tumor types including melanoma." (PMID 28562667, 2017). "In addition to inhibiting PTN activity, menin also suppresses melanoma growth and progression through the activation of the TGFβ signaling pathway." (PMID 39336822, 2024). "In addition, the silencing of PTN was also reported to inhibit the tumor angiogenesis in vivo by counting the blood vessels, indicating PTN is a promising target for the therapy of melanoma." (PMID 28562667, 2017). "Several other genes were targeted in melanoma cells by in vitro studies, as the anti-apoptotic factor survivin, the transcription factor c-myc and the growth factor pleiotrophin." (PMID 12085193, 2002). "Inactivation of the PTN gene with PTN-targeted hammerhead ribozyme constructs has inhibited PTN-induced colony formation and prevents tumor growth in mice, suggesting that PTN may be playing major role in the metastatic growth of melanoma cells." (PMID 30427932, 2018). "In humans, the PTN gene is involved in carcinogenesis including mitogenesis, metastasis and angiogenesis, and it is expressed in a variety of cancers, such as lung, colon, prostate, breast and pancreas as well as melanomas, neuroblastomas and many carcinoma cell lines." (PMID 22496782, 2012). "Pleiotrophin (PTN) is a secreted cytokine that is expressed in various cancer cell lines and human tumor such as colon cancer, lung cancer, gastric cancer and melanoma." (PMID 28562667, 2017). "The ERK/MAPK and PI3K/Akt signaling pathways are key drivers of melanoma growth and progression, and overexpressing menin decreases the protein levels of pFAK, pERK1/2, and PI3K, partially through inhibition of PTN and RPTPβ/ζ activity." (PMID 39336822, 2024). "PTN interaction with RPTPβ/ζ leads to dephosphorylation and activation of c-Src and subsequently of ανβ3, FAK, phosphoinositide 3-kinase (PI3K) and ERK1/2 in lung cancer and melanoma cells." (PMID 30427932, 2018). "Although the molecular events responsible for their activity remain to be defined, the upregulation of PTN, RGS13, and SPARC in black color skin could explain the incidence of melanoma in light coat color horses." (PMID 28974924, 2018).
Alzheimer disease (9 papers, 2017 to 2025). A progressive, neurodegenerative disease characterized by loss of function and death of nerve cells in several areas of the brain leading to loss of cognitive function such as memory and language. "LDL receptor-related protein (LRP) is a receptor of midkine and pleiotrophin and it is genetically linked to Alzheimer’s disease." (PMID 28101734, 2017). "Upregulated MDK and PTN expression has been found following CNS injury and neurodegenerative diseases, including ischemic stroke, Alzheimer's disease, and multiple system atrophy." (PMID 37269057, 2023). "Furthermore, the importance of mitochondrial dysfunction and other proteins, such as midkine and pleiotrophin, in the pathogenesis of Alzheimer’s disease is increasingly recognized." (PMID 39940772, 2025). "PTN is a small cationic protein that has been extensively studied in various physiological processes such as tissue repair, tumors, neural regeneration, adipose differentiation, and Alzheimer’s disease." (PMID 37810257, 2023). "Indeed, PTN is upregulated in Parkinson’s Disease (PD), Alzheimer’s Disease (AD), acute ischemic brain injury and different forms of drug abuse." (PMID 35046956, 2021). "Midkine and pleiotrophin are involved in neurodegenerative diseases such as Alzheimer’s disease." (PMID 28101734, 2017). "Taking together, these studies may be of relevance since PTN is found highly upregulated in different brain disorders characterized by neuroinflammation such as Parkinson’s disease, Alzheimer’s disease, addictive disorders, tumors, and ischemia." (PMID 28259175, 2017).
brain tumors (9 papers, 2012 to 2025). "PTN abundance and function in the CNS has naturally resulted in it being studied in the context of brain tumors." (PMID 36828390, 2023). "This suggests antagonism of PTPRZ1 antagonism by PTN as a possible therapeutic approach for many primary brain tumor types." (PMID 36966348, 2023). "Conversely, PTN expression is increased in a number of human cancers, in particular brain tumors and is thought to be involved in tumor angiogenesis." (PMID 29531016, 2018). "The comparison of gene expression in these two groups shows that patients with higher expression levels of PTN or of ALK in their brain tumors had perished by the chosen time whereas patients with lower levels were still alive." (PMID 23267434, 2012). "In normal adult tissues, however, only limited expression of the full-length ALK receptor, PTN or MK was seen but overexpression of these genes was reported in a number of human cancers including brain tumors." (PMID 23267434, 2012). "To determine if PTN affected the histological subtype of PDGFB-induced tumors, we examined the histopathology of the brain tumors." (PMID 27806344, 2016). "Primary GBM used to be the most common and developed in patients with no prior record of brain tumors, with EGFR overexpression, PTN (MMC I) mutation, and CDKN2A (p16) deletion." (PMID 39202515, 2024). "We conclude that increased PTN expression is not sufficient for brain tumor initiation in neonatal Arf -/- mice." (PMID 27806344, 2016).
neuroblastoma (9 papers, 2003 to 2023). Neuroblastoma (NB) is the most common solid, extracranial childhood tumor. "First, the effect of increasing concentrations of PTN on MPP+-induced SH-SY5Y cell viability loss was tested in the Methyl Thiazolyl Tetrazolium (MTT) assay 24 h after treatment of neuroblastoma SH-SY5Y cells with PTN and/or MPP+." (PMID 34206170, 2021). "This interaction was verified in mammalian cells and the hippocampus and neocortex in the rat brain, and PTN increased tyrosine phosphorylation of GIT1/Cat-1 in B103 neuroblastoma and mouse oligodendrocyte-lineage OL1 cells." (PMID 37175798, 2023). "In primary neuroblastoma tumours, two neurotrophic factors, pleiotrophin (PTN) and midkine (MDK), are highly expressed and have been postulated to bind and activate ALK in vitro." (PMID 34769149, 2021). "PTN mRNA expression in neuroblastoma correlates with favorable prognosis, and in an in vivo neuroblastoma xenograft model, PTN gene expression was found down-regulated in tumors resistant to irinotecan therapy, as compared to sensitive tumors." (PMID 34957126, 2021). "Studies have demonstrated that MK and PTN are involved in several types of carcinomas; the overexpression of MK or PTN correlated with a poor prognosis for patients with neuroblastomas, urinary bladder carcinomas, and papillary thyroid cancer." (PMID 32153561, 2020). "PTN is highly expressed in favourable neuroblastomas, whereas it is expressed at a significantly lower level in advanced tumours." (PMID 17531100, 2007). "We previously reported that MK mRNA expression is elevated in neuroblastoma specimens at all stages, whereas pleiotrophin, the other member of the MK family, is expressed at high levels in favourable neuroblastomas." (PMID 12771916, 2003). "Interestingly, the other MK family member, PTN, is expressed at high levels in favourable neuroblastomas." (PMID 12771916, 2003). "In neuroblastoma cells, this leads to increased tyrosine phosphorylation of p190 RhoGAP, GIT1, and DNER, and it has been proposed that the PTN inhibitory effect on PTPRZ1 acts as a major ALK indirect activating mechanism." (PMID 34957126, 2021). "The scramble siRNA exerted a very limited effect on cytoprotection, and only at a doxorubicin concentration of 10−7 M. A parallel study carried out with pleiotrophin siRNA did not affect the cytoprotective activity of doxorubicin resistant cells on wild neuroblastoma cells (data not shown)." (PMID 24083030, 2013).
pancreatic cancer (9 papers, 2015 to 2025). "Our previous studies showed that the miR-137 inhibits pancreatic cancer cell proliferation, invasion and chemoresistance through targeting PTN in pancreatic cancer." (PMID 30866999, 2019). "Exhibiting a proto-oncogene function, PTN is mainly up-regulated in many types of tumors, such as breast, prostate, and pancreatic cancers, acting as an angiogenic factor." (PMID 25617851, 2015). "T the circ‐LDLRAD3/miR‐137‐3p/PTN axis slows the progression of pancreatic cancer." (PMID 35588441, 2022). "The high expression level of PTN combined with N‐syndecan may contribute to the increased perineural invasion and poor prognosis of pancreatic cancer." (PMID 28557334, 2017). "For example, in pancreatic cancer, PTN is a target of microRNA-137 and may promote cellular resistance to 5-fluorouracil treatment." (PMID 28969035, 2017). "Activation of PTN signaling could promote perineural invasion in the pancreatic cancer." (PMID 40416874, 2025). "Of the five most used proteins in the BTC signatures (IL-6, IL-15, PTN, CCL23, and MUC-16), only IL-6 was used in the primary pancreatic cancer signatures." (PMID 36831406, 2023). "As a model of human PDAC, we used the human pancreatic cancer cell line COLO357PL, which carries mutant KRAS and expresses FGFR and ALK receptors as well as the ALK ligand PTN." (PMID 35326668, 2022). "Similarly, the ALK ligand pleiotrophin (PTN) is elevated in serum and tissues from pancreatic cancer patients, and it has been shown that PTN levels are associated with the malignant progression of human pancreatic cancer, demonstrating the clinical significance of this signaling pathway." (PMID 35326668, 2022).
COVID-19 (8 papers, 2021 to 2025). A disease caused by infection with severe acute respiratory syndrome coronavirus 2. "This is consistent with the previous findings in which PTN was elevated at the mRNA level in the upper airway of patients with COVID-19 as well as patients with COVID-19 over the age of 60." (PMID 37047248, 2023). "Using machine learning, we identified a set of diagnostic plasma biomarkers (e.g., TRIM21, CASP8, PTN and CSF1) that had very high accuracy in differentiating COVID-19 from CAP, and outperformed standard laboratory parameters used in clinical practice." (PMID 36829233, 2023). "Higher levels of PTN were observed in both COVID-19 cohorts compared to healthy controls and other sepsis cohorts, excluding septic shock." (PMID 36829233, 2023). "Very few proteins had higher levels in COVID-19 compared to sepsis in this study, among them PTN and KRT19." (PMID 36829233, 2023). "In contrast, only two proteins, pleiotrophin (PTN) and keratin-19 (KRT19), were upregulated in COVID-19." (PMID 36829233, 2023). "However, they found three markers, E3 ubiquitin-protein ligase (TRIM21), Pleiotrophin (PTN), and Caspase-8 (CASP8), that differentiated COVID-19 from community-acquired pneumonia sepsis more accurately than standard clinical markers." (PMID 39859366, 2025). "Finally, through machine learning, we identified biomarkers, such as TRIM21, PTN and CASP8, that accurately differentiated COVID-19 from CAP-sepsis with higher accuracy than standard clinical markers." (PMID 36829233, 2023). "In addition, the plasma proteome alterations identified unique features associated with respective disease, allowing the discovery of potential plasma biomarkers for differential diagnosis of COVID-19 and CAP-sepsis, among them TRIM21, PTN and CASP8." (PMID 36829233, 2023). "Fifteen proteins were significantly increased in the severe group in comparison to healthy controls, of which pleiotrophin (PTN), adhesion G protein-coupled receptor G1 (ADGRG1) and C-C motif chemokine ligand 19 (CCL19) were the top three proteins most elevated in patients with severe COVID-19." (PMID 39767799, 2024). "In COVID-19 patients, reduced levels of ENTPD2 and PTN were observed in nonsurvivors of ICU stay, even after adjustment." (PMID 35967328, 2022).
lung carcinoma (8 papers, 2002 to 2025). "Similarly, PTN can stimulate the proliferation and migration of lung cancer cells, and serum PTN levels are associated with lung cancer progression." (PMID 38766528, 2024). "PTN is a heparin-binding growth factor that is highly expressed in certain solid cancers, such as in breast and lung cancers." (PMID 40416874, 2025). "Both mRNA and protein levels of VEGF-D and PTN decreased with miR-200 overexpression and Nrp2 knockdown, and reportedly promoted the migration and metastasis of lung cancer cells." (PMID 38766528, 2024). "The relationship between serum PTN level and clinicopathological characteristics in patients with lung cancer was nanlyzed." (PMID 30635982, 2019). "The expression of PTN transcripts was determined in tumour specimens obtained from five lung cancer patients." (PMID 11953815, 2002). "In most of the lung cancer patients (81%), we found serum levels of pleiotrophin above those of control subjects (P<0.001)." (PMID 11953815, 2002). "Under these conditions, serum concentrations of PTN were elevated in 81% of all investigated lung cancer patients, in 63% of NSCLC patients (P<0.002) and in 87% of SCLC patients (P<0.001)." (PMID 11953815, 2002). "Additionally, treatment with recombinant VEGF-D and PTN proteins promoted the migration and invasion of lung cancer cells." (PMID 38766528, 2024). "However, the potential role of serum PTN levels in early diagnosis and prognosis of lung cancer, especially SCLC, a type of lung cancer, still requires further investigation." (PMID 30635982, 2019). "Our result, that the serum PTN concentration in lung cancer patients correlates positively with the stage of disease, supports the hypothesis that PTN is produced by the tumour tissue." (PMID 11953815, 2002). "This hypothesis is further supported by our finding of PTN-mRNA expression in lung cancer specimens." (PMID 11953815, 2002). "In contrast, we show here that the measurement of serum PTN concentration may offer an effective marker of lung cancer, particularly of SCLC, with the possibility to monitor the response to therapy." (PMID 11953815, 2002). "Furthermore, the functional significance of PTN as a potent angiogenic factor in lung cancer clearly merits further investigation." (PMID 11953815, 2002). "Our study suggests that pleiotrophin may be an early indicator of lung cancer and might be of use in monitoring the efficacy of therapy, which needs to be confirmed by larger studies." (PMID 11953815, 2002). "In conclusion our results indicate that PTN might be a prognostic factor for lung cancer and larger prospective further studies are required to confirm this hypothesis." (PMID 11953815, 2002). "Furthermore, in lung adenocarcinoma, menin and polycomb-mediated repression of PTN transcription and is proposed as an epigenetic mechanism that controls the PTN–ALK signaling pathway and hence can inhibit lung cancer progression." (PMID 23267434, 2012). "Our data might give a preliminary indication for a longer survival of lung cancer patients with lower PTN serum levels as compared to the survival of lung cancer patients with higher PTN serum levels (not shown)." (PMID 11953815, 2002).
Parkinson disease (8 papers, 2011 to 2024). A progressive degenerative disorder of the central nervous system characterized by loss of dopamine producing neurons in the substantia nigra and the presence of Lewy bodies in the substantia nigra and locus coeruleus. "PTN expression levels are upregulated in the nigrostriatal pathway of Parkinson’s Disease (PD) patients." (PMID 35246557, 2022). "PTN is upregulated in the brain in different pathologies characterized by exacerbated neuroinflammation, including Parkinson’s disease." (PMID 34206170, 2021). "Pleiotrophin is known to promote the survival and differentiation of dopaminergic neurons in vitro and is up-regulated in the substantia nigra of Parkinson's disease patients." (PMID 21649894, 2011). "We undertook, what may seem, a challenging path to decide on the potential of PTN as a neuroprotective therapy in Parkinson's disease." (PMID 21649894, 2011). "Here we have studied the distribution of PTN in the substantia nigra and the effect of PTN over-expression as a potential trophic factor influencing the fate of dopaminergic neurons undergoing degeneration in an animal model of Parkinson's disease." (PMID 21649894, 2011). "Pleiotrophin could then become a potential therapeutic tool, for the design of strategies of neuroprotection and neurorestoration in Parkinson's disease." (PMID 21649894, 2011). "However, the data agree in that PTN could be of potential benefit in Parkinson's disease." (PMID 21649894, 2011).